EGFR (epidermal growth factor receptor)
Diseases named in the same sentence as EGFR in open-access papers (continued):
Sharing a sentence is not in itself a finding about the gene and the disease.
tumor (continued). "In vivo studies revealed dose-dependent tumor suppression and rapid EGFR degradation (24 h) by compound 12c in PC-9 xenografts, alongside favorable safety profiles." (PMID 40724826, 2025). "By sequestering miR‐7, ciRS‐7 upregulates target genes like EGFR, which are central to tumor development and progression." (PMID 39991629, 2025). "This synergy is likely attributable to the ability of cetuximab to bind to the EGFR on tumor cells, flagging them for destruction by NK cells." (PMID 40063100, 2025). "The system showed enhanced EGFR-specific targeting and tumor homing in A431 models, outperforming the unmodified platform." (PMID 39940134, 2025). "For instance, Listeria monocytogenes and F. nucleatum can activate RTKs like ErbB2, ErbB3, and EGFR, promoting tumor growth and resistance to RTK-targeted therapies in CRC." (PMID 39948481, 2025). "Malignant proliferative cell populations serve as the primary drivers of tumor expansion, characterized by the high expression of proliferation markers such as KI-67 and EGFR." (PMID 40255400, 2025). "We have constructed a novel bi-specific (412a), dual-payload ADC by attaching an antibody targeting EGFR and cMET that are overexpressed in many tumor types." (PMID 40870990, 2025). "The study also found that extracellular PKM2 activates the EGFR pathway in a self-secretory manner, promoting tumor cell growth and inducing EGFR phosphorylation." (PMID 40137167, 2025). "By halting tumor cell growth and spread, cetuximab helps in the deactivation of EGFR while stimulating the internalization and degradation of the receptor." (PMID 40881676, 2025). "Applying a low threshold for positivity as membranous staining in more than 1% of tumour cells, they reported EGFR expression in 61.7% of cases." (PMID 40940907, 2025). "While MET amplification confers resistance to anti-EGFR therapies in CRC, this resistance can be overcome by MET kinase inhibitors, which restore sensitivity to EGFR blockade and significantly inhibit tumor growth." (PMID 40526090, 2025). "Upon binding to one of its seven native ligands, EGFR is activated, dimerises and promotes cell proliferation, contributing to tumor growth." (PMID 40697381, 2025). "Given the central role of EGFR in HNSCC tumor biology, multiple agents have been tested to inhibit this signaling pathway." (PMID 41018114, 2025). "For example, IDH mutations are ubiquitously expressed and remain stable over time, whereas EGFR amplification demonstrates marked spatial variability between different tumor regions and frequently occurs and disappears over time." (PMID 40197845, 2025). "Immunosuppression and immune evasion by MDSCs are also mediated by epidermal growth factor receptor- mitogen-activated protein kinases (EGFR-MAPK) - dependent upregulation of PD-L1 expression on tumor cells." (PMID 40230862, 2025). "Epidermal growth factor receptor (EGFR)‐overexpressing A431 tumor cells were incubated with an mAb‐IR700 targeting EGFR and exposed to light." (PMID 40830817, 2025). "During these studies, no radiographic responses to therapy were observed, and relapsed tumor cells expressed wild-type EGFR protein while demonstrating substantial intratumoral infiltration by suppressive regulatory T-cells." (PMID 41154636, 2025). "These interactions create a feed-forward loop in which EGFR signaling induces the release of proinflammatory cytokines, while inflammation, in turn, sustains EGFR pathway activation and tumor progression." (PMID 41268168, 2025). "This rationale supports artificial reconstruction of the immune synapse by forcibly bridging NKG2D-CAR-engineered NK cells to EGFR/ERBB2-positive tumor cells, thereby overcoming immune escape and addressing intratumoral heterogeneity." (PMID 41209565, 2025). "EGFR plays a pivotal role in the initiation, progression, and metastasis of tumor cells by activating many downstream pathways in CRC, such as RAS/RAF/MEK/ERK and PI3K/AKT/mTOR pathway." (PMID 40959565, 2025).
tumor (continued). "Co-incubation of EGFR-positive tumor cells with anti-EGFR CAR-T cells resulted in the release of high levels of cytokines such as IL-2, IL-4, IL-10, TNF-α, and interferon (IFN)-γ, within 24 hours." (PMID 39995659, 2025). "EGFR is related to the inhibition of tumor cell proliferation, angiogenesis, tumor invasion, metastasis and apoptosis." (PMID 39907159, 2025). "En un contexto neoadyuvante, las terapias anti-EGFR pueden reducir el tamaño del tumor y mejorar las tasas de resección." (PMID 40977824, 2025). "By specifically binding tumor-associated antigens (e.g., CD19 or EGFR) and CD3 on T cells, they activate cytotoxic responses precisely at the tumor site, reducing systemic toxicity." (PMID 39982231, 2025). "An oncolytic vaccinia virus armed with an Epha2-directed BiTE and the oncolytic adenovirus ICOVIR-15K expressing an EGFR-targeting BiTE, respectively, showed robust T-cell activation and bystander cell-mediated cytotoxicity in vitro and in murine tumor models." (PMID 39789356, 2025). "The multiplex immunofluorescence staining clearly demonstrated the co-expression of B7H3 and EGFR on the membrane of tumor cells." (PMID 41291854, 2025). "Taken together, this evidence suggests the efficacy of anti-EGFR therapy even among the elderly when properly selected based on tumor molecular profile and sidedness." (PMID 41154394, 2025). "It exploits the high-affinity binding of antibodies to tumor-specific antigens (e.g., bevacizumab against VEGF, cetuximab against EGFR) to enable tumor-targeted imaging." (PMID 41305285, 2025). "Strikingly, DNAJC10-OE A172 xenografts displayed significantly reduced tumor infiltration and prolonged survival compared to Vector controls, mirroring results from wild-type EGFR-expressing U87 models." (PMID 41191192, 2025). "The resulting nanoagents exhibited rapid internalization, potent cytotoxicity in EGFR-positive cancer cells, as well as strong tumor targeting and antitumor effects in vivo." (PMID 41304914, 2025). "In contrast, the in vivo treatment of patient #1 PDX tumor-bearing mice confirmed the parallel ∼ 2.5-fold upregulation of EGFR and AREG." (PMID 39864337, 2025). "Stratified analysis of major clinicopathological parameters including sex, age, smoking status, EGFR status, and tumor‐node‐metastasis (TNM) stage confirmed a survival benefit for the CDSI‐high group (log‐rank test, p < 0.01)." (PMID 40443719, 2025). "Circulating tumor DNA (ctDNA) studies, in cases of acquired resistance to anti-EGFR therapies, have allowed the identification of genomic alterations such as RAS and other molecular drivers, in tumors initially diagnosed as wild type (WT)." (PMID 39941081, 2025). "The observed increase in EGFR and its downstream effectors p-AKT and ERK2 is consistent with the recognized role of EGFR signaling in promoting tumor growth, proliferation, and survival through activation of the PI3K/AKT and MAPK/ERK pathways." (PMID 41304988, 2025). "Gefitinib (ZD1839) is a potent, selective, and orally active EGFR tyrosine kinase inhibitor that inhibits EGF-stimulated tumor cell growth by blocking EGF-induced EGFR autophosphorylation in tumor cells." (PMID 40041495, 2025). "When TERT or GABPB1 were inhibited simultaneously with EGFR, the combination treatment resulted in enhanced inhibition of cell and tumor growth as well as animal survival compared not only to controls but also to any of the single treatments." (PMID 40463649, 2025).
tumor (continued). "The EGFR signaling pathway is a central driver of tumor growth, but inhibitors like osimertinib often face resistance." (PMID 41381443, 2025). "Mutations in genes such as EGFR, PDGF Receptor Alpha (PDGFRA), and Neurofibromin 1 (NF1) are considered driver mutations that define distinct clonal populations and contribute to tumor heterogeneity." (PMID 40358199, 2025). "Particularly, in HNSCC, both WBP5 and EGFR expressions were significantly upregulated in tumor tissues compared to those in normal samples." (PMID 40002180, 2025). "EGFR mCAR T cells demonstrated robust, antigen-dependent cytotoxic activity, resulting in specific lysis of more than 90% of EGFR-expressing tumor cells after 24 h of co-incubation." (PMID 41516067, 2025). "In EGFR-mutated NSCLC, immunosuppressive cytokines such as IL-6, VEGF, and TGF-β are elevated, which contribute to immune evasion and tumor progression." (PMID 40733125, 2025). "Due to the decrease in the number of EGFR proteins on the cell surface, tetrahydroxycurcumin inhibits the growth of tumor cells and makes their proteins insensitive to their ligands." (PMID 41179371, 2025). "Overactivation of the epidermal growth factor receptor (EGFR) is prevalent in various tumours, rendering it a promising target for cancer therapy, particularly in the treatment of non-small cell lung cancer (NSCLC)." (PMID 40172117, 2025). "Here, we concentrated on EGFR-TKI-resistant NSCLC to delineate how ZEB2 remodeled the TME, with emphasis on tumor-associated macrophage (TAM) dynamics." (PMID 40510028, 2025). "The current phase 2 clinical trial (NCT05393466) aims to evaluate the safety, tolerability, pharmacokinetics, and anti-tumour activity of BPI-361175 in advanced NSCLC patients with EGFRC797S mutation and other EGFR related mutations." (PMID 40172117, 2025). "Surface modification strategies, such as PEGylation or the conjugation of targeting ligands like EGFR antibodies, offer the potential for tumor-specific accumulation while reducing off-target effects." (PMID 40535810, 2025). "Cabozantinib potentiates CAR-NK92 activity by upregulating EGFR expression and downregulating PD-L1 on tumor cells, thereby improving immune cell infiltration and reducing immune suppression within the tumor microenvironment." (PMID 40677703, 2025). "This complementary mechanism—involving simultaneous inhibition of EGFR (by AFT) and MET (by HAD-B1)—likely underlies the enhanced tumor suppression observed with the combination therapy." (PMID 40430565, 2025). "EGFR is widely distributed on the surface of many cell membranes, such as epithelial cells, fibroblasts, glial cells, tumor cells, and so on." (PMID 40299971, 2025). "Tumor EGFR status can be evaluated by more than a dozen different methods, and the inconsistency in detection can lead to different results, which increases the variability between studies." (PMID 40574864, 2025). "Due to the heterogeneity of tumour cells, the resistance mechanisms substantially differ according to the specific EGFR-TKIs used." (PMID 41257744, 2025). "Honokiol inhibited tumor cell proliferation (half maximal effective concentration: 3.3 – 7.4 μM), induced apoptosis, and suppressed key EGFR downstream signaling pathways, including MAPK, AKT, and STAT3." (PMID 41019287, 2025). "Based on these studies, this research focused on the interaction between EGFR-TKI-resistant NSCLC tumor cells and TAMs, aiming to elucidate the inducement of M2 polarization and inhibition of M1 polarization of TAMs in TKI-resistant microenvironment." (PMID 40510028, 2025). "In lung cancer, elevated GBP1 is linked to erlotinib resistance, serving as a prognostic warning for EGFR-targeted therapies and detectable via quantitative PCR (qPCR), proteomic assays, or circulating tumor DNA analysis." (PMID 40564939, 2025). "Collectively, we found that the four anti-EGFR/anti-B7H3 bsAbs had greater binding affinity to tumor cells compared with cetuximab, especially FH-EB02." (PMID 41291854, 2025).
tumor (continued). "Early-stage tumors were enriched in pro-inflammatory microglia, whereas late-stage tumors exhibited a predominance of anti-inflammatory macrophages and myeloid-derived suppressor cells (MDSCs), correlating with BBB disruption and EGFR+ tumor expansion." (PMID 40076502, 2025). "Our study reveals that in EGFR-mutant NSCLC, a minor EGFR-low expressing tumor clone can be essential to the development of drug resistance over time by microenvironmental modifications potentiating the tumor regrowth." (PMID 39747003, 2025). "EGFR was chosen as target antigen since EGFR is a validated target for tumor therapy and extensive data on EGFR-targeting scTRAIL fusion proteins have been generated in the past." (PMID 40328809, 2025). "In EGFR-dependent resistance mechanisms, tumor cell proliferation depends largely on EGFR signaling." (PMID 40277748, 2025). "There was a 94.7% agreement between ctDNA and tumor tissue for KRAS and EGFR mutations, reinforcing the reliability of ctDNA for molecular profiling." (PMID 40426987, 2025). "EGFR, a transmembrane protein linked to CRC, showed low tumor expression but higher levels in normal mucosa, scar tissue, and muscle post-nCRT in our study, reducing its specificity as an FGS target." (PMID 40563608, 2025). "The overactivation of NADPH oxidase, ROS-induced OS resulting from MITO dysfunction, and ectopic expression of antioxidative enzymes play a role in EGFR-mediated tumor progression and drug resistance to EGFR TKIs." (PMID 40563358, 2025). "Receptor degradation was observed in tumor samples for both EGFR and cMET 24 h after two doses of TAVO412, as compared to control tumors." (PMID 40452841, 2025). "Such mRNA-modified T cells (STAREGFR-T cells) have been analyzed for anti-EGFR bispecific TCE secretion and for their ability to drive anti-tumor responses against EGFR-expressing cells, both in vitro and in vivo." (PMID 41341587, 2025). "JHU-083 has been demonstrated to be highly effective against EGFR-driven lung tumorigenesis, with the capacity to promote adaptive T-cell-mediated tumor-specific immune responses that enhance evasion." (PMID 40598593, 2025). "The results showed that compared to the control group, the cell culture supernatants of the P1 and P4 treatment groups had higher levels of EGFR, indicating that P1 and P4 promoted the release of tumor cell membrane antigens." (PMID 40733687, 2025). "The in vivo efficacy was evaluated in mice with solid Ehrlich Ascites Carcinoma (EAC), focusing on tumor volume, oxidative stress, inflammatory cytokines, Epidermal Growth Factor (EGFR) expression biomarkers, and histopathological analysis." (PMID 41599143, 2025). "Proteolysis targeting chimeras (PROTACs) have been utilized to overcome drug resistance by degrading mutant EGFR, but most are restricted to their poor cell permeability and insufficient tumor‐targeting ability." (PMID 40842076, 2025). "The nanoparticles, which are loaded with an EGFRvIII-derived peptide, can be inserted into the tumour membrane and are recognised by an EGFR targeting CAR." (PMID 41465327, 2025). "Previous studies reported that p-EGFR and other receptor tyrosine kinases can be detected in EVs purified from the plasma of tumor-bearing mice and from the conditioned media of cultured cancer cells." (PMID 40210802, 2025). "Ultimately, akin to BAPN or LOX gene ablation, CCT365623 downregulates MATN2, impeding EGFR plasma membrane localization in tumors and inhibiting tumor growth and metastasis in mice." (PMID 39979279, 2025).
tumor (continued). "To examine pathway differences between GBM and LUAD, we compared co-regulated EGFR genes between these tumor types." (PMID 39959305, 2025). "While it will be interesting to investigate the role of nuclear EGFR in these additional immune cell types, the current in vitro data demonstrates that nuclear EGFR can directly impact the expression of NK cell activation antigens in tumor cells." (PMID 39521886, 2025). "The combination of Crizotinib (c-Met pathway inhibitor) and Erlotinib (EGFR pathway inhibitor) shows synergistic effects in various tumor models." (PMID 40662801, 2025). "This tumour group showed significantly better survival after primary surgical as well as radio- or radiochemotherapy or anti-EGFR treatment." (PMID 40655928, 2025). "We aim to evaluate the tumor-targeting specificity of cetuximab-IRDye800CW (Cet-IRDye800CW), an epidermal growth factor receptor (EGFR)-specific near-infrared probe, for fluorescence-guided surgery in CRC models." (PMID 41346398, 2025). "For instance, epidermal growth factor receptor (EGFR) and cyclin D1 can be detected through mRNA analysis and can be correlated with tumor progression or a poor prognosis." (PMID 40096320, 2025). "Teliso-V, a MET-targeted ADC, combined with osimertinib, reported an ORR of 50% and a mPFS of 6.8 months in patients with MET overexpressed (MET 3 or higher staining in ≥25% tumor cells) EGFR-mutant NSCLC progression on osimertinib." (PMID 40470164, 2025). "EGFR mutations (e.g., exon 19 deletions, L858R) are prevalent in LUAD and drive constitutive activation of EGFR tyrosine kinase, promoting tumor proliferation and metastasis via PI3K-AKT and MAPK-ERK pathways, which regulate cell cycle progression." (PMID 41154834, 2025). "Beyond its role in regulating the phenotype and function of malignant cells, EGFR also plays a crucial role in modifying the external microenvironment to drive the development of tumors, particularly by promoting tumor angiogenesis." (PMID 39816681, 2025). "Further, treatment of liposomes encapsulating CMTM4-specific siRNA significantly reduced tumor growth in vivo, which can further synergize with EGFR inhibitor to enhance the therapeutic outcomes." (PMID 39948411, 2025). "When conjugated to an EGFR-targeting ligand, the chimeric siRNA was delivered to and internalized by tumor cells." (PMID 40762837, 2025). "For example, tumor cells with highly activated EGFR are more sensitive to strong static magnetic fields, exhibiting significant proliferation inhibition, while normal cells or EGFR-low-expressing cells are unaffected." (PMID 40635706, 2025). "A key breakthrough was the identification of EGFR, as a driver of tumor growth and metastasis, and its expression in HNC." (PMID 40426875, 2025). "The individual tumor comparison also showed that the CIN z-score was numerically higher in tumors that acquired EGFR-TKI resistance compared to tumors before EGFR-TKI treatment (−0.223 vs. 0.204, respectively)." (PMID 40136696, 2025). "Using different xenograft and allograft models, we show that the sorafenib-EGFR-TKI combination can delay tumor growth and promote the recruitment of inflammatory cells." (PMID 40846697, 2025). "Despite reduced responsiveness to conventional chemotherapy, Scissor+ tumor cells were sensitive to EGFR inhibitors, providing insights into clinical intervention strategies for WT patients at high risk of recurrence." (PMID 40098972, 2025). "This engineering allowed for selective viral entry exclusively through the targeted receptors in mice bearing CD38- or EGFR-positive human tumor xenografts, effectively eliminating the interactions with native receptors." (PMID 40573393, 2025). "Specificity for EGFR was then confirmed by blocking experiments wherein an excess dose of cetuximab reduced tumor uptake by 48.8% in biodistribution analyses and by 56.7% in PET imaging, confirming tracer-target engagement." (PMID 41211421, 2025).